INS (insulin)
Diseases named in the same sentence as INS in open-access papers (continued):
Sharing a sentence is not in itself a finding about the gene and the disease.
myocardial ischemia (continued). "Thus, it would be an advantage to promote insulin-independent endosomal recycling of Glut-4 for treating cardiac ischemia, in terms of I/R-triggered insulin resistance." (PMID 32839388, 2020). "The baseline FFA levels could be influenced by a number of factors, such as infections and myocardial ischemia through catecholamine-induced responses, in addition to hormones (e.g., insulin) and blood lipids." (PMID 32724675, 2020). "In fact, malonyl-CoA decarboxylase knockout (MCD-/-) mice that exhibit diminished cardiac β-oxidation do not undergo diet-induced loss of cardiac insulin sensitivity and glucose utilization and are protected from cardiac ischemia and reperfusion injury." (PMID 24116221, 2013). "Therefore, restoring the insulin sensitivity by sEH suppression can be associated with the better mitochondrial efficacy demonstrated in our results by the enhanced ATP production and RCR in a myocardial ischemia model." (PMID 27375480, 2016). "Measurements included: 1) serum glucose and insulin, 2) total energy expenditure per metabolic body size (Wt3/4), 3) respiratory quotients (in the fed and fasted states), 4) changes in plasma lipids, 5) the relative mitochondrial amount in liver and heart, and 6) indices related to cardiac ischemia." (PMID 21814553, 2011). "Elevated basal Akt phosphorylation (without insulin stimulation) was induced by myocardial ischemia." (PMID 26659007, 2015). "Thus, it is imperative to develop therapies that promote plasma membrane transport of Glut-4, independent of insulin, during cardiac ischemia." (PMID 32839388, 2020).
cystic fibrosis (42 papers, 2005 to 2026). Autosomal recessive disorder caused by pathogenic variants in the CFTR gene (cystic fibrosis transmembrane conductance regulator), which encodes a chloride and bicarbonate channel expressed in epithelial cells, and follow the diagnosis criteria. "Cluster 4 (yellow) contains 15 keywords such as acute autotransplantation, children, chronic pancreatitis, cystic fibrosis gene, independence, insulin, risk, mutation, total pancreatectomy with islet autotransplantation (TPIAT), yield, and hereditary pancreatitis." (PMID 40747090, 2025). "While this study may provide an early signal of the association of prepuberal insulin secretory indices with short adult stature in cystic fibrosis, these findings should be confirmed in larger studies." (PMID 35358060, 2022). "We aimed at studying insulin signal transduction in cystic fibrosis and wild-type cells to establish differences and investigate whether insulin sensitivity was altered in cystic fibrosis and related to CFTR loss of function." (PMID 25299696, 2014). "In fact, an increased ratio of secreted Proinsulin/Insulin predicts future risk of T2D in otherwise “healthy” adults and is also seen in patients with Cystic Fibrosis, who have a 50% lifetime risk of developing Cystic Fibrosis Related Diabetes (CFRD)." (PMID 32433667, 2020). "Summary of studies suggesting insulin treatment improves pulmonary function and nutritional status in patients with cystic fibrosis with early glucose abnormalities." (PMID 41552835, 2026). "Even in preclinical stages, patients with cystic fibrosis frequently exhibit delayed and diminished insulin secretion, particularly in response to oral glucose intake." (PMID 40842499, 2025). "Lastly, the study emphasizes the significance of longitudinally tracking glucose and insulin dynamics in patients diagnosed with cystic fibrosis, specifically those with borderline Matsuda Index values." (PMID 41300682, 2025). "This study investigated the prevalence of cystic fibrosis-related diabetes (CFRD) in the Croatian cystic fibrosis population, the age at diagnosis, insulin requirements, and the relationship between age at diagnosis and other clinical parameters." (PMID 40430241, 2025). "For patients with cystic fibrosis, in usual practice, the objective is to conduct observations of consultations dedicated to the discussion of insulin therapy, individual semistructured interviews, and questionnaires." (PMID 39874570, 2025). "The results of a study indicate that glycemic irregularities manifest at an early stage in individuals with cystic fibrosis, potentially due to inadequate insulin production." (PMID 37893045, 2023). "Nevertheless, a reduction of HMGB1 expression was also found in an epithelial bronchial cell model for cystic fibrosis, after in vitro insulin exposure." (PMID 37256493, 2023). "Defective CFTR protein, responsible for Cystic Fibrosis, is highly expressed in pancreatic ductal epithelial cells (PDECs) but their impact on insulin secreting pancreatic islets is not fully understood." (PMID 31311920, 2019). "The time burden, on the other hand, was frequently assessed, with interventions aiming at reducing the time required per insulin injection, minimizing dosing frequency in cystic fibrosis treatment, or decreasing the travel time for patients requiring phototherapy sessions." (PMID 33434200, 2021). "However, for cystic fibrosis, airway epithelial cells seemed to be an appropriate screening model to address for the first time a molecular study on insulin signal transduction." (PMID 25299696, 2014). "Insulin secretory defects in cystic fibrosis were initially shown in small-sized studies that employed various sophisticated techniques such as the hyperglycemic clamp and intravenous glucose tolerance test (IVGTT)." (PMID 35358060, 2022).
cystic fibrosis (continued). "Furthermore, aerosol therapies have developed over the years and such treatment examples now comprise drug deliveries by inhalation (e.g. oral inhalation of insulin), inhaled gene therapy (e.g. treating cystic fibrosis), and vaccination by inhalation (e.g. inhaled measles or flu vaccine)." (PMID 25885473, 2015). "Chronic inflammation in cystic fibrosis leads to elevated cytokine levels, such as TNF-α and IL-6, which interfere with insulin signaling." (PMID 40842499, 2025). "In the pancreas, CF-related pancreatic damage results in an inability to secrete sufficient insulin to maintain normal blood glucose concentration, leading to a unique type of diabetes known as cystic fibrosis-related diabetes (CFRD) which affects up to 40%–50% of adults with CF." (PMID 38084404, 2024). "Studies have shown that the elevation of acyl-ghrelin (AG) in individuals with cystic fibrosis may be related to AG-mediated inhibition of insulin secretion." (PMID 39569809, 2024). "Nevertheless, in the context of cystic fibrosis, there is an atypical excessive generation of reactive oxygen species (ROS), which leads to detrimental effects on the pancreatic β-cells responsible for insulin release." (PMID 37893045, 2023). "Considering that standard OGTT cannot detect insulin secretion defects, we implemented a modified OGTT protocol in three separate and geographically distributed cystic fibrosis Italian centers, expanding the previously studied Milan cohort of PwCF." (PMID 36983651, 2023). "According to UK Cystic Fibrosis Registry data, 89% of people receiving treatment for CFRD are prescribed insulin, and the corresponding figure from the US CF Registry is 81%, which equates to approximately a third of all adults with CF in each country receiving insulin." (PMID 36382232, 2022). "The European Cystic Fibrosis Society (ECFS) registry does not report the date at diagnosis of CFRD, but rather the age at CFRD diagnosis is calculated as the difference between the year in which the patient began insulin and the year of birth." (PMID 40430241, 2025).
gout (42 papers, 2005 to 2025). A condition characterized by painful swelling of the joints, which is caused by deposition of urate crystals. "Lansoprazole is associated with a lower risk of gout compared to other PPIs, potentially due to its unique ability to improve insulin resistance through metabolic modulation." (PMID 40459644, 2025). "Collectively, these results highlight that HU extends far beyond purine metabolism or gout-related pathology and is linked with atherogenic lipid abnormalities, insulin resistance, and markers of vascular dysfunction." (PMID 41373369, 2025). "Additionally, HNF4A can also control gene expression in pancreatic islets, potentially further associating with uric acid and gout by affecting insulin secretion." (PMID 35813212, 2022). "After removing rs780094 in the GCKR gene according to leave-one-out analysis, recalculating the main IVW estimate suggested a causal effect of fasting insulin on increased serum urate (β = 0.802, 95% CI: 0.514–1.090, P < 0.001) and risk of gout (OR = 3.293, 95% CI: 1.030–10.532, P = 0.045)." (PMID 35992130, 2022). "These associations lead us to speculate that improved insulin resistance might play a role in skeletal muscle mass gain in gout patients undergoing ULT." (PMID 34594303, 2021). "Future studies should determine whether interleukin-1 blockade, pharmacologic insulin sensitization, or uric acid-lowering therapy is effective to reduce the risk for HF among adults with gout." (PMID 32299504, 2020). "Obesity and its associated metabolic syndrome are major risk factors for the development of gout, and weight loss has been shown to promote uric acid excretion and improve insulin sensitivity, which has a positive effect against gout attacks." (PMID 38877436, 2024). "Uric acid inhibitors, used to treat gout and related symptoms, are widely known to improve insulin sensitivity." (PMID 39728460, 2024). "Our analysis showed that genetically predicted fasting insulin, BMI, TG, blood pressure, and ALT were robust associated with gout or serum urate." (PMID 35992130, 2022). "Scopoletin not only has an antidiabetic effect on enhancing PM- GLUT4 expression in 3T3-L1 adipocytes and has been considered as an AMPK activator for insulin signaling regulation, but also has effects on gout by inhibiting urate crystal induced inflammation." (PMID 35083262, 2021). "One subject had worsening of his gout, but this was felt to be unrelated to inhaled insulin treatment." (PMID 31470605, 2019). "At baseline, the majority of diabetic gout patients were receiving either insulin or oral hypoglycaemic agents (225/312; 72.1%)." (PMID 23683134, 2013). "Deliberate weight reduction in a group of patients with gout was accompanied by reduction of insulin resistance and less numbers of inflammatory events." (PMID 15871736, 2005). "In a large study on T2DM patients treated with metformin or insulin, which used an international federated database, a statistically significant decrease in the incidence of gout was observed 5 years after the introduction of SGLT2 inhibitors, but not with GLP-1 mimetics." (PMID 40733074, 2025). "The hPDI assessed in this study may help to prevent gout indirectly by improving insulin sensitivity." (PMID 38771576, 2024). "Our results confirm that the associations between fasting insulin and serum urate are causal, but not gout." (PMID 35992130, 2022). "In the IVW analysis, fasting insulin-associated SNPs in Europeans showed no causal effect on increased serum urate and risk of gout (P = 0.287 and P = 0.635, respectively)." (PMID 35992130, 2022). "Consequently, the link between the TG/HDL ratio and gout may be due to a mechanism involving insulin resistance." (PMID 39866735, 2024). "The SNPs that were selected to create the GRS for gout can be connected into functional or biochemical pathways, including renal and gut excretion of uric acid and the carbohydrate metabolic pathway, which includes the regulation of glycolysis, glucose, and insulin." (PMID 35484537, 2022).
gout (continued). "Two p-wave duration scores (p = 0.043 and 0.038) and gout (p = 0.041) were significantly higher in BCS vs control, while fasting insulin (p = 0.046) and insulin sensitivity index (p = 0.052), were significantly lower in BCS compared to HC." (PMID 39057719, 2024). "Second, while our studyincluded all patients with T2DM and gout regardless of their antidiabetictreatment regimen, this may have introduced some heterogeneity within thecontrol group, particularly if a higher proportion of insulin users was includeddue to advanced disease progression." (PMID 40300646, 2025). "Although insulin concentrations were not measured in this study, the levels of glucose, TCA cycle intermediates, and pyruvate and lactate, which are the main products of glycolysis, tended to be higher in patients with gout." (PMID 38397902, 2024).
hypophosphatemia (42 papers, 1997 to 2026). Lower than normal levels of phosphates in the circulating blood. "Acute hypophosphatemia can be caused by an intracellular shift, such as with hyperventilation or treatment of ketoacidosis with insulin." (PMID 41146174, 2025). "This indicates that hypophosphatemia-associated impaired glucose metabolism is related to decreased tissue sensitivity to insulin." (PMID 36364739, 2022). "The administration of insulin induces the intracellular shift of glucose and phosphorus into the skeletal muscle and liver cells, leading to hypophosphatemia, especially if there is an underlying situation of phosphate depletion." (PMID 36614129, 2022). "For instance, use of insulin has been established as a risk factor for hypophosphatemia in dogs and cats." (PMID 33763464, 2021). "On another note, chronic hypophosphatemia was shown to be inversely associated with insulin sensitivity and glucose tolerance in healthy subjects." (PMID 27941661, 2016). "Carbohydrate administration, which can cause hypophosphatemia by increasing insulin secretion, accelerating glycolysis, and inducing intracellular shifts of phosphate, is a common cause of hypophosphatemia in hospitalized patients." (PMID 18159256, 2007). "However, a definition solely based on serum phosphate levels might induce a bias, especially in critically ill patients, where other conditions like alkalosis, insulin and glucose supply, and renal replacement therapy may also cause hypophosphatemia." (PMID 38612956, 2024). "Days alive and hospital-free, health care costs, hypophosphatemia and serum lactate were often omitted from insulin infusion studies, suggesting a valuable endpoint for investigation." (PMID 40407548, 2025). "The onset of anabolic processes leads to potassium uptake into the insulin-stimulated cell, resulting in severe hypophosphatemia, changes in the electrochemical potential of the membrane, arrhythmias, and heart failure." (PMID 37705405, 2023). "During insulin protocols, asymptomatic hypophosphatemia occurred in 75% and in 61.4% of dogs in Group L and in Group R, respectively." (PMID 33195532, 2020). "This is of interest since the renal proximal tubule contains the Na-dependent phosphate cotransporters (NPT2a and NPT2c) and hypophosphatemia negatively regulates insulin synthesis and sensitivity." (PMID 24839967, 2014). "Treatment of HYP-mice with SPR4 peptide resulted in striking beneficial changes in serum glucose, insulin, leptin, osteocalcin, sclerostin, fat mass, 1.25(OH)2D3, and calcium with a partial correction of the hypophosphatemia." (PMID 24839967, 2014). "Insulin administration also can lead to mild hypophosphatemia, because it decreases cellular acidity." (PMID 15706766, 1997). "During treatment, insulin administration and correction of metabolic acidosis promote a shift of phosphate from the extracellular to the intracellular compartment, further exacerbating hypophosphatemia." (PMID 40766915, 2025). "DM may also lead to hypophosphatemia via several mechanisms, e.g. osmotic diuresis (in inadequate glucose control), treatment with insulin or sodium-glucose cotransporter-2 (SGLT2) inhibitors, malabsorption and reduced vitamin D levels." (PMID 40183914, 2025). "The absence of these minerals in the “maintenance fluids” associated with the shift of phosphorus to intracellular compartment after glycose infusion and insulin release may contribute to the hypophosphatemia." (PMID 39599631, 2024). "Insulin secretion in itself is directly related to hypophosphatemia." (PMID 38590318, 2024). "As said, the rapid insulin release in response to refeeding can lead to hypophosphatemia." (PMID 37705405, 2023). "IUGR infants in fact are malnourished during intrauterine life: at birth, with the start of TPN, the insulin level increases and promotes the entry of phosphate in the cells, inducing hypophosphatemia and hypokaliemia in an anabolic phase in which requests are high." (PMID 38004147, 2023).
hypophosphatemia (continued). "In nondiabetic subjects, hypophosphatemia has been shown to be associated with reduced insulin sensitivity." (PMID 36364739, 2022). "Although we did not have data about urine phosphate, hypophosphatemia is likely related to the phosphaturic effect associated with glycosuria more than the potential intracellular shift due to an excess of insulin." (PMID 36614129, 2022). "None of the dogs showed the clinical signs associated with hypophosphatemia during the insulin protocols." (PMID 33195532, 2020). "Our data suggest that Pi transport into myocytes is stimulated by insulin, a hormone markedly induced during refeeding, which may provide a pathophysiologic explanation to the hypophosphatemia observed." (PMID 27338702, 2016). "Hypophosphatemia could also impair pancreatic insulin secretion." (PMID 36364739, 2022). "Hypophosphatemia in this population may be the result of multiple factors, including refeeding syndrome, ß adrenergic catecholamine stimulation, infection, hyperventilation, carbohydrate intake and insulin, traumatic brain injury, and increased energy expenditure." (PMID 38732640, 2024). "In Group R, 3/11 had mild to moderate hypophosphatemia (1.5, 1.94, and 2.57 mg/dL, respectively), but none of them received preventive supplementation before insulin administration." (PMID 33195532, 2020). "Although insulin more likely plays a contributory, rather than principal, role in producing hypophosphatemia in alcoholic patients, there are clinical implications to consider." (PMID 15706766, 1997). "Moreover, starvation alone does not lead to hypophosphatemia, as there is lack of insulin and increased cell catabolism which releases phosphate from cells." (PMID 40183914, 2025). "On the basis of our prior ST-[31P]MRS studies in humans that showed that insulin stimulation of muscle mitochondrial VATP correlated with intracellular Pi concentrations, we next tested the hypothesis that hypophosphatemia decreases muscle Pi uptake and VATP in NaPi2a−/− mice." (PMID 27338702, 2016).